IGFBP3 (insulin like growth factor binding protein 3)
Diseases named in the same sentence as IGFBP3 in open-access papers (continued):
Sharing a sentence is not in itself a finding about the gene and the disease.
glioma (28 papers, 2013 to 2025). A benign or malignant brain and spinal cord tumor that arises from glial cells (astrocytes, oligodendrocytes, ependymal cells). "Notably, the overexpression of IGFBP3 can restore the tumorigenesis of glioma caused by YTHDF2 deletion in vivo." (PMID 38463397, 2024). "In this study, we analyzed immune cells infiltration in gliomas and found that IGFBP3 may be associated with an immunosuppressive microenvironment." (PMID 38326861, 2024). "Similarly, all subgroups in lower grade glioma were significantly associated with IGFBP-3 expression, with lower expression indicative of better survival outcome (FDR < 5.82∙10−2)." (PMID 32443727, 2020). "In addition, the expression of IGFBP3 was also increased in gliomas, and associated with IDH1/2 mutations status, histology and tumor grade, it was suggested that IGFBP3 may be a prospective new target for the therapy of glioma." (PMID 38326861, 2024). "For instance, insulin-like growth factor binding protein 3 (IGFBP-3), Cullin1 (Cul1), Golgi phosphoprotein 3 (GOLPH3), and aquaporin 1 (AQP1) have all been associated with glioma progression and invasiveness." (PMID 40867240, 2025). "Our results indicated that glioma patients with high expression of IGFBP3 or PD-L1 had a lower survival." (PMID 38326861, 2024). "The role of IGFBP3 in the glioma immune microenvironment was investigated using the CIBERSORT algorithm." (PMID 38326861, 2024). "Our studies showed that naive CD4 T cell infiltration was reduced in the tumor microenvironment of glioma patients with high IGFBP3 expression." (PMID 38326861, 2024). "Following, our investigation aimed to determine if there existed a correlation between IGFBP3/PD-L1 gene expression and the overall survival (OS) of individuals with gliomas." (PMID 38326861, 2024). "A study was conducted on patients with high-grade gliomas to investigate the relationship between serum concentrations of serum IGF-1 and IGFBP-3 and the risk of depression." (PMID 37834128, 2023). "In conclusion, the proliferative potential of glioma cells is inhibited by miR-133a-5p, which reduces IGFBP3 synthesis." (PMID 35966888, 2022). "The findings confirmed that IGFBP3 was overexpressed in glioma tissues compared to para-cancerous tissues." (PMID 35966888, 2022). "The IGFBP3 overexpression effectively counteracts the glioma cell proliferation-inhibiting impact of miR-133a-5p." (PMID 35966888, 2022). "In this study, an IGFBP3 overexpression vector and a miR-133a-5p mimic were transfected in glioma cells." (PMID 35966888, 2022). "It was revealed that IGFBP3 overexpression reverses the inhibitory effect of miR-133a-5p on glioma cell proliferation." (PMID 35966888, 2022). "Analysis of published studies from TCGA database on IGFBP3 expression in glioma revealed that IGFBP3 was strongly elevated in glioma tissues (low-grade glioma (LGG) and glioblastoma multiforme (GBM)) compared to para-cancerous tissues." (PMID 35966888, 2022). "It was shown that IGFBP3, IGFBP5, and IGFBP7 were highly expressed in glioma and were associated with higher tumor grade and poorer survival, consistent with our study." (PMID 35992105, 2022). "The top 20 network analysis indicated that PTX3, TIMP1, CHI3L1, LTF and IGFBP3 comprise a crucial role in gliomas progression." (PMID 36153549, 2022). "This work established the role of IGFBP3/miR-133a-5p axis in the glioma cell proliferation at the cellular level in vitro." (PMID 35966888, 2022). "Impediment of neoplasm growth after depleting IGFBP3 is regarded as a promising strategy for glioma treatment." (PMID 35387222, 2022). "IGFBP3 and IGFBP5 were overexpressed in gliomas and were associated with higher tumor grade and lower survival." (PMID 35992105, 2022). "Following transfection with miR-133a-5p mimics or inhibitors, the IGFBP3 protein expression in glioma cells was determined by western blotting." (PMID 35966888, 2022).
glioma (continued). "This study demonstrated that IGFBP3 is the target gene of miR-133a-5p and that increasing miR-133a-5p can inhibit glioma cells from expressing IGFBP3 protein." (PMID 35966888, 2022). "The colony formation assay was applied to evaluate the influence of IGFBP3 overexpression on the miR-133a-5p in glioma cell proliferation." (PMID 35966888, 2022). "For assessment of the IGFBP3 expression in glioma tissues and prognosis, TCGA database was employed." (PMID 35966888, 2022). "The target gene of miR-133a-5p was identified as IGFBP3 using bioinformatics predicted analyses in this study, which aimed to expand our understanding of the mechanism of miR-133a-5p in glioma cell proliferation." (PMID 35966888, 2022). "IGFBP3 overexpression can drastically counteract the inhibitory activity of miR-133a-5p on glioma cell growth." (PMID 35966888, 2022). "In vitro studies suggested that IGFBP3 knockdown suppressed cell proliferation and interruption of the G2/M cell cycle, in addition to apoptosis in glioma cells." (PMID 33902430, 2021). "In support of this, PDGFD and PDGFRB were positively correlated with a three-gene signature (TGFBI, IGFBP3, and CHI3L1) associated with glioma tumor cell invasion and migration and poor patient survival." (PMID 34539622, 2021). "Expression of a three-gene signature, comprised of TGFBI, IGFBP3, and CHI3L1, has previously been associated with glioma tumor cell invasion and migration and poor patient survival." (PMID 34539622, 2021). "Analysis of the survival effect of IGFBP-3 expression in all cancers identified its highly significant effect on survival in glioma (FDR = 1.51∙10−32 (Hazard Ratio, HR = 4.39))." (PMID 32443727, 2020). "As well as IGFBP-2, also IGFBP-3 improves glioma cell migration, invasion and proliferation in an IGF-independent manner." (PMID 33604294, 2020). "To determine whether IGFBP3 is related to the regulation of glioma immune microenvironment, we comprehensively analyzed immune cells infiltration in gliomas using the CIBERSORT algorithm." (PMID 38326861, 2024). "Recently, a study reported that IGFBP3 may play a role in the immune microenvironment in hypertrophic cardiomyopathy, but its role in glioma immune microenvironment is still unclear." (PMID 38326861, 2024). "Based on previous studies and our preliminary results, therefore, we hypothesized that IGFBP3 performs an important role in regulating PD-L1 expression in gliomas." (PMID 38326861, 2024). "In addition, the higher expression of IGFBP3 was positively correlated with a worse glioma and GBM prognosis." (PMID 33902430, 2021). "Survival in pan-kidney cohort (KICH+KIRC+KIRP), lower grade glioma, mesothelioma, colorectal adenocarcinoma was similarly affected by IGFBP-3 to a lesser extent (FDR = 1.74∙10−6 (HR = 2.73), 1.25∙10−5 (HR = 2.36), 1.22∙10−3 (HR = 2.98), 3.87∙10−3 (HR = 2.20), respectively)." (PMID 32443727, 2020). "Given the high significance of IGFBP-3 gene expression on survival outcome in glioma (FDR = 1.51∙10−32 (HR = 4.39)), it was unsurprising that IGFBP-3 expression affected survival in nearly all glioma subgroups (FDR < 2.90∙10−2), with lower expression being associated with better survival outcome." (PMID 32443727, 2020). "Furthermore, Chia-Hua Chen demonstrated that IGFBP-3 silencing suppresses glioma cell proliferation by G2/M cell cycle arrest." (PMID 33604294, 2020). "Overexpression of connexin-43 in C6 glioma cells results in decreased levels of IGFBP-3 and increased levels of IGFBP-4 and it may be responsible for the reduced proliferative capacity." (PMID 24175938, 2013). "Interestingly, as one of upstream regulator of IGFBP3, HoxD10 inhibits the migration and invasion of glioma and gastric cancer cells partly by modulating the expression of MMP14 and uPAR, which are both tumor invasion promoting factors." (PMID 24386080, 2013). "Therefore, we hypothesized that IGFBP3 may be involved in the immunosuppressive microenvironment of gliomas." (PMID 38326861, 2024).
glioma (continued). "The findings indicated that while multiple factors contribute to the development of depression in cancer patients, the pathogenesis of IGFBP-3, specifically in the progression of the gliomas, may play a significant role in comparison to patients without gliomas." (PMID 37834128, 2023). "It reduces glioma cell proliferation by modulating IGFBP3 and could be a target for glioma therapy." (PMID 35966888, 2022). "In glioma and GBM proneural subgroup patients, higher expression level of IGFBP3 is related to shorter overall survival." (PMID 38206646, 2024). "The results from the Oncomine database showed that IGFBP2, IGFBP3, IGFBP4, and IGFBP5 were expressed at a higher level in tissues from patients with brain and CNS cancer than in normal tissues from healthy individuals." (PMID 35832140, 2022). "Using the polymerase chain reaction, GBM cell lines were found to express mRNA for IGFBP genes: IGFBP-1 in 42%, IGFBP-2 in 65%, IGFBP-3 in 97%, IGFBP-4 in 3%, IGFBP-5 in 74%, IGFBP-6 in 94%, and IGFBP-7 in 87% of glioma cell lines." (PMID 35832140, 2022). "Based on the data from the Oncomine database, the transcriptional levels of IGFBP2, IGFBP3, IGFBP4, and IGFBP5 were observed to be elevated in brain and CNS cancer." (PMID 35832140, 2022). "The upregulation of CCNB1, CDK1, CXCL8, IGFBP3, MYBL2, SERPINE1 also notably indicated poor overall survival of glioma patients (HR>1, P=0.000<0.05)." (PMID 34512164, 2021). "IGFBP-3, IGFBP-4 and IGFBP-5 transcripts are significantly higher in GBM compared to low-grade gliomas or normal samples, supporting their role in the pathogenesis of gliomas." (PMID 33604294, 2020). "There are also reports that IGFBPs, including IGFBP3, are overexpressed in gliomas compared to non-tumor brain tissue and with higher levels of expression observed in high-grade gliomas." (PMID 40522948, 2025). "IGFBP3 is a member of the insulin-like growth factor binding protein (IGFBP) family and has also been shown to play a role in the pathogenesis of diverse malignancies, including gliomas." (PMID 38612480, 2024). "In addition, 5 hub genes in hub network 2 were related to the poor prognosis of gliomas, including F5, IGFBP5, TNC, SCG3, and IGFBP3." (PMID 35387222, 2022).
hepatocellular carcinoma (26 papers, 2005 to 2025). A malignant tumor that arises from hepatocytes. "In a recent study on hepatocellular carcinoma, IGFBP3 was found highly expressed associated with disease poor prognosis." (PMID 36153549, 2022). "After controlling for some data (hepatitis infection, BMI, smoking and alcohol abuse), a higher molar difference of IGFBP3 and IGF1 was connected with a decreased hepatoma risk, more than IGFBP3 alone." (PMID 29702590, 2018). "There are also studies that suggested the reactivation of IGFBP3 reduces the invasiveness of hepatocellular carcinoma cells in children, whereas several studies have reported that the abnormal expression of IGFBP3 has the carcinogenic effect." (PMID 37397026, 2023). "In hepatocellular carcinoma cells, overexpression of IGFBP3 induces apoptosis of hepatocellular carcinoma cells and reduces colony formation." (PMID 35966888, 2022). "Significant AUC of IGFBP3 against healthy controls was observed in cholangiocarcinoma and hepatocellular carcinoma." (PMID 27579675, 2016). "IGFBP3 discriminated hepatocellular carcinoma from either healthy controls or IDACP with an AUC of more than 0.8." (PMID 27579675, 2016). "Our observations of promoter hypermethylation in human hepatocellular carcinomas and derivative cell lines, and the observations in this report strongly support the notion that IGFBP3 is a true tumor suppressor gene." (PMID 15661074, 2005). "IGFBP3 is a gene that is silenced by biallelic hypermethylation or hypermethylation and loss of heterogeneity (LOH) in human hepatocellular carcinoma." (PMID 15661074, 2005). "We identified a hot spot of promoter hypermethylation in human hepatocellular carcinoma and its cell lines in the promoter upstream region of IGFBP-3." (PMID 15661074, 2005). "We previously reported a hot spot of promoter hypermethylation of IGFBP-3 in human hepatocellular carcinomas and derivative cell lines." (PMID 15661074, 2005). "Given the potential role of IGFBP3, we hypothesized that IGFBP3-related genetic features might be valuable for predicting the prognosis and treatment of hepatocellular carcinoma." (PMID 37397026, 2023). "However, serum IGFBP3 levels in hepatocellular carcinoma patients were significantly lower than those in healthy individuals." (PMID 36409444, 2022). "Moreover, epigallocatechin-3-gallate has been shown to decrease IGF1 and restore IGF binding protein 3 (IGFBP3) levels in hepatocellular carcinoma cells." (PMID 28885570, 2017). "Furthermore, IGFBP2 or 3 exhibited a relatively low AUC (<0.8) for discriminating IDACP from other malignancies, except hepatocellular carcinoma in the case of IGFBP3." (PMID 27579675, 2016). "Silencing of IGFBP3 expression through hypermethylation of CpG islands within the promoter region has been described in several cancers, including gastric, breast, colorectal ovarian, and hepatocellular carcinomas." (PMID 24964199, 2014). "Trichostatin A (TSA) treatment could increase Sp1-mediated IGF binding protein 3 (IGFBP-3) promoter activity in hepatoma." (PMID 23148884, 2012). "As gene silencing may occur without mutations, we recently investigated IGFBP-3 promoter hypermethylation in human hepatocellular carcinoma." (PMID 15661074, 2005). "Being up-regulated in hepatocellular carcinoma cells, miR-155 can increase expression of IGF-II and IGF-1R, while decreasing IGFBP-3 expression." (PMID 33768092, 2021). "Previous studies have supported an association between serum insulin-like growth factor-1 (IGF1) and IGF-binding protein 3 (IGFBP3) levels and hepatocellular carcinoma (HCC), but the results were inaccurate." (PMID 29113370, 2017).
hepatocellular carcinoma (continued). "However, the AUC values of IGFBP2 and 3 between most malignancies and IDACP were not so high (AUC < 0.8), except in the case of IGFBP3 for hepatocellular carcinoma, suggesting that these proteins have limited specificity for IDACP diagnosis." (PMID 27579675, 2016).
colon cancer (24 papers, 1997 to 2024). "IGFBP3 has been demonstrated to cause apoptosis and inhibit proliferation in colon cancer cell lines, in addition to its IGF-binding characteristics." (PMID 34858769, 2021). "Insulin, IGF-1, and IGFBP-3 have also been linked with colon cancer in both in vitro and in vivo studies." (PMID 24732966, 2014). "The risk of colon cancer was positively correlated with plasma IGFBP-3." (PMID 33414813, 2020). "This association might be explained by the biological hypothesis that increased levels of circulating free IGF-1 and decreased levels of insulin-like growth factor binding protein-3 (IGFBP-3) can increase colon cancer risk." (PMID 29484135, 2018). "Consistent with the report, in primary colon cancer, high IGFBP3 expression showed significantly poorer prognosis than low IGFBP3 expression (p = 0.0028) totally differently from CD8A." (PMID 38557819, 2024). "The involvement of IGFBP-3 in the inhibition of cell growth is evident when human IGFBP-3 cDNA is transfected into mammalian cell lines like colon cancer cells, human breast cells and mouse fibroblast cells." (PMID 32478064, 2020). "The weight of evidence surely implicates this gene as a prominent driver of CRC cancer aggressiveness despite its being at odds with older studies connecting IGFBP3 expression to an anti-proliferative effect on the growth of colon cancer cells." (PMID 24988459, 2014). "Several but not all prospective studies have found evidence for a positive association between higher levels of IGF-1 or the molar ratio of IGF-1 and its primary binding protein, IGF-binding protein 3 (IGF-1/IGFBP-3 ratio) and colorectal and/or colon cancers." (PMID 22216097, 2011). "Our study highlights the importance of considering plasma as well as tissue IGFBP-3 in the early stages of colon tumor development, consistent with recent reports on tissue IGFBP-3 in colon cancer." (PMID 18498652, 2008). "IGFBP-3 induces apoptosis and inhibits proliferation in human breast, lung, prostate and colon cancer cells in vitro and in experimental animal models of colon carcinoma." (PMID 18498652, 2008). "In other cell lines such as human airway smooth muscles cells and colon cancer cells, IGFBP-3 has been shown to act as a potent proliferative agent." (PMID 12085194, 2002). "In summary, we found that shikonin suppresses colon cancer cell proliferation and migration through cellular experiments and identified eight genes (CCNB3, IL-1α, CXCL8, CDKN2A, MYC, IGFBP3, SQSTM1, and GADD45G) associated with cell senescence through systematic bioinformatics analysis." (PMID 39188951, 2024). "Several but not all prospective studies have found high IGF-1 or IGF/IGFBP-3 ratio and high C-peptide to be associated with an increased risk of colorectal or colon cancer." (PMID 22216097, 2011). "Colon tumors were counted, and cytokines, insulin-like growth factor 1 (IGF-1), IGF binding protein 3 (IGFBP-3), adipokines, proliferation, apoptosis, and expression of microRNAs (miRs) were measured." (PMID 24732966, 2014). "Multivariable adjusted ORs and 95% confidence intervals of colorectal and colon cancer by median levels of IGF-1, C-peptide, IGF-1/IGFBP3 ratio and vitamin D, HPFS and NHS combined." (PMID 22216097, 2011). "Colon cancer extracts were able to degrade exogenous IGFBP-2, IGFBP-3 and IGFBP-4, whereas normal tissue extracts were without effect on IGFBP-2." (PMID 9218734, 1997).